MDM2 (MDM2 proto-oncogene)
Diseases named in the same sentence as MDM2 in open-access papers (continued):
Sharing a sentence is not in itself a finding about the gene and the disease.
Thrombocytopenia (continued). "Thus, inhibition of Mdm2 in MSCs contributes to thrombocytopenia after IR." (PMID 36909480, 2023). "This may contribute to the generally greater toxicity of MDM2 inhibitors for cancer cells compared to normal cells, although some haematopoetic cell lineages also appear to be sensitive, as evidenced by the dose limiting thrombocytopenia seen in the early phase clinical trials of MDM2 inhibitors." (PMID 27223080, 2016). "Early-generation MDM2 inhibitors (e.g., RG7112, Idasanutlin) showed limited monotherapy efficacy and dose-limiting toxicities like thrombocytopenia, halting their development at early-phase clinical trials." (PMID 41901322, 2026). "Prevalence of anemia, thrombocytopenia and anti-SSB were significantly higher in pSS patients with anti-MDM2 autoantibody." (PMID 28147328, 2017). "Prevalence of anemia, thrombocytopenia and anti-SSB was significantly higher in pSS patients with anti-MDM2 autoantibody." (PMID 28147328, 2017). "Thrombocytopenia, a side effect shared by MDM2 inhibitors and clinically approved drugs for GBM (TMZ, lomustine (CCNU)), poses a challenge for the integration of these agents with MDM2 inhibitor-based regimens." (PMID 37509518, 2023). "As with most MDM2 inhibitors that have so far reached clinical trials, side effects of NVP-CGM097 include thrombocytopenia and neutropenia which would need to be considered in any clinical application in combination with drugs with overlapping toxicity profiles such as CDK4/6 inhibitors." (PMID 32787886, 2020).
esophageal cancer (27 papers, 1999 to 2025). A primary or metastatic malignant neoplasm involving the esophagus. "The correlation between MDM2 T309G single nucleotide polymorphism and esophageal cancer susceptibility was demonstrated by the odds ratio (OR) and its corresponding 95% confidence interval (95% CI)." (PMID 31970867, 2020). "Chen and colleagues discussed the 309 T > G SNP and esophageal cancer risk by meta‐analysis in year 2015 and found that MDM2 T309G SNP was correlated with esophageal cancer susceptibility." (PMID 31970867, 2020). "Here, we provide an updated meta‐analysis relevant to MDM2 T309G single nucleotide polymorphism and esophageal cancer susceptibility by adding new publications." (PMID 31970867, 2020). "Based on the present data, there was a significant correlation between MDM2 T309G single nucleotide polymorphism and esophageal cancer susceptibility." (PMID 31970867, 2020). "The pooled data showed there was a significant correlation between MDM2 T309G single nucleotide polymorphism and esophageal cancer susceptibility." (PMID 31970867, 2020). "In the present updated meta‐analysis, nine case‐control studies relevant to MDM2 T309G single nucleotide polymorphism and esophageal cancer susceptibility were included." (PMID 31970867, 2020). "By systematic searching the databases of Medline, EMBASE, CBM and CNKI, the case‐control or cohort studies related to MDM2 T309G single nucleotide polymorphism and esophageal cancer risk were screened." (PMID 31970867, 2020). "The aim of this study was to investigate the correlation between MDM2 T309G single nucleotide polymorphism (SNP) and esophageal cancer susceptibility through pooling the open published data." (PMID 31970867, 2020). "Since five years have now past, several new studies have been published which are relevant to MDM2 T309G single nucleotide polymorphism and esophageal cancer susceptibility." (PMID 31970867, 2020). "Although the exact pathogenesis of how SNP changes MDM2 and cancer susceptibility are not fully understood, a significant correlation between MDM2 T309 G SNP and esophageal cancer has been confirmed by our present meta‐analysis." (PMID 31970867, 2020). "In contrast, transcript levels of both MTF2 and MDM2 are elevated in diffuse large B-cell lymphoma and esophageal carcinoma, whereas both MTF2 and MDM2 transcripts are down-regulated in malignant ovarian cancer (serous cystadenocarcinoma)." (PMID 37895228, 2023). "ATF3 has been reported to affect the degradation of MMP2 at the protein level via the ATF3/MDM2/MMP-2 complex in esophageal cancer cells." (PMID 29966001, 2018). "In patients with esophageal cancer, many prognostic markers, including cyclinD1 and mouse double minute 2 homolog (MDM2), have been reported." (PMID 27600761, 2016). "In patients with esophageal cancer, many prognostic markers, including cyclin D1, E-cadherin, and MDM2, have been reported." (PMID 28536608, 2016). "Lastly, esophageal cancer often exhibits intrachromosomal amplification of MYC, ERBB2, EGFR, RB1, GATA4/6, CCND1, RTK and MDM2 as well as ecDNA-associated amplification of MYC and MDM2." (PMID 41415205, 2025). "Without statistical heterogeneity, the odds ratio for MDM2 T309G single nucleotide polymorphism and esophageal cancer susceptibility was pooled by the fixed effect model." (PMID 31970867, 2020).
leiomyosarcoma (27 papers, 1994 to 2026). An uncommon, aggressive malignant smooth muscle neoplasm, usually occurring in post-menopausal women. "Combination effects of MDM2 antagonists and a MEK inhibitor were analyzed in a patient-derived xenograft mouse model and in DDLPS and leiomyosarcoma cell lines using different cell proliferation assays and immunoblot analysis." (PMID 32806555, 2020). "Indeed, combining an MDM2 antagonist and a CDK4 inhibitor resulted in an antagonistic effect in myxofibrosarcoma (IB114) and leiomyosarcoma (IB136) cells, indicating that the synergistic effect was specific to the DDLPS histological subtype." (PMID 28629371, 2017). "The IHC results for MDM2 and CDK4 were negative in leiomyosarcoma and positive in DDLPS in over 90% of the cases." (PMID 39588302, 2024). "In the present case, the leiomyosarcomatous component showed no immunopositivity for MDM2 and CDK4; however, some leiomyosarcomas show positivity for MDM2 and CDK4." (PMID 23971887, 2013).
endometrial cancer (24 papers, 2009 to 2025). Primary or metastatic malignant neoplasm involving the endometrium (mucous membrane that lines the endometrial cavity). "The MDM2 T309G polymorphism (rs2279744) is widely studied in gynecological cancers like cervical, ovarian, and endometrial cancer." (PMID 36981012, 2023). "The MDM2 promoter SNP55 (rs2870820) T-allele was also associated with a reduced risk of endometrial cancer before 50 years of age." (PMID 34170849, 2021). "In conclusion we find the MDM2 SNP del1518 del variant to be associated with reduced risk of endometrial cancer among individuals carrying the SNP309TT genotype, an observation warranting confirmation in independent studies." (PMID 28158999, 2017). "We found the MDM2 del1518 del variant to be associated with reduced risk of endometrial cancer among individuals carrying the MDM2 SNP309TT genotype." (PMID 28158999, 2017). "This meta-analysis suggests that MDM2 SNP309 polymorphism contributes to endometrial cancer susceptibility, especially in Caucasian populations." (PMID 24423195, 2013). "Our meta-analysis based on eight case–control studies suggested that the MDM2 SNP309 polymorphism contributes to increased endometrial cancer susceptibility." (PMID 24423195, 2013). "When stratified according to the quality of the articles, we found that the MDM2 SNP309 polymorphism was associated with elevated endometrial cancer risk in both high and low quality studies in additive model (CC vs. CG) and recessive model (GG vs. TG + TT)." (PMID 24423195, 2013). "The MDM2 SNP309 G/G genotype increases the risk of endometrial cancer in Caucasians and in Japanese women." (PMID 23624782, 2013). "Several studies have previously suggested that the MDM2 SNP309 polymorphism was associated with an increased risk of endometrial cancer." (PMID 24423195, 2013). "In this study we assessed the impact of MDM2 del1518 on risk of ovarian and endometrial cancer." (PMID 28158999, 2017). "In conclusion, this meta-analysis suggests that the MDM2 SNP309 polymorphism may be associated with increased risk of developing endometrial cancer particularly among Caucasians." (PMID 24423195, 2013). "Our search identified six original studies of the association between MDM2 SNP rs2279744 (also referred to as SNP309) and endometrial cancer, all of which found a statistically significant increased risk per copy of the G allele." (PMID 32066633, 2020).
endometrial cancer (continued). "Given that MDM2 appears to play a critical role in endometrial cancer, control of NFκB p50 homodimer provides the possibility for a new therapeutic target." (PMID 26293665, 2015). "In this study, we attempted to confirm that ASE of MDM2 occurs in vivo in cancer-free endometria and in endometrial cancer." (PMID 26293665, 2015). "Our findings suggest that both the SNP55 status and the NFκB p50 activity are important in the transcriptional regulation of MDM2 in endometrial cancers." (PMID 26293665, 2015). "While SNP309G enhances Sp1 transcription factor binding and MDM2 transcription, SNP285C antagonizes Sp1 binding and reduces the risk of breast-, ovary- and endometrial cancer." (PMID 25327560, 2014). "We previously demonstrated that the Ras/ER/MDM2 pathway is important for proliferation of endometrial cancer cells in vitro." (PMID 23624782, 2013). "Currently there were only two studies on MDM2 SNP309 polymorphism and endometrial cancer risk in Asian populations, and the genotype distributions in the control population of one study was deviate from HWE." (PMID 24423195, 2013). "As new studies emerge, to provide the most comprehensive assessment of the associations between the MDM2 SNP309 polymorphism and endometrial cancer risk, we performed a meta-analysis of all available studies." (PMID 24423195, 2013). "All studies published up to August 2013 on the association between MDM2 SNP309 polymorphism and endometrial cancer risk were identified by searching electronic databases PubMed, Web of Science, EMBASE, and Chinese Biomedical Literature database (CBM)." (PMID 24423195, 2013). "To date, a number of epidemiological studies have evaluated the association between MDM2 SNP309 polymorphism and endometrial cancer risk, but the results remain inconclusive." (PMID 24423195, 2013). "Statistical significant heterogeneity among studies was observed in the association analysis between the MDM2 SNP309 polymorphism and endometrial cancer risk in the overall populations (GG vs. GT + TT: PQ < 0.001)." (PMID 24423195, 2013). "The association between the MDM2 SNP309 polymorphism and endometrial cancer risk was assessed by odds ratios (ORs) together with their 95% confidence intervals (CIs)." (PMID 24423195, 2013). "Over the last two decades, a number of molecular epidemiological studies have been conducted to investigate the association between the MDM2 SNP309 polymorphism and endometrial cancer risk, but the results remain inconsistent." (PMID 24423195, 2013). "In contrast, we found no synergistic effects between MDM4 SNP34091 and MDM2 SNPs with respect to endometrial cancer risk (data not shown)." (PMID 26867771, 2016). "This indicated that MDM2 is critical to the development of endometrial cancer." (PMID 26293665, 2015). "In a previous study, we found MDM2 SNP285 status to correlate to stage in endometrial carcinomas." (PMID 22558411, 2012).
endometrial cancer (continued). "Hence, it is biologically reasonable to hypothesize a potential relationship between the MDM2 SNP309 polymorphism and endometrial cancer risk." (PMID 24423195, 2013). "With respect to the current meta-analysis, the effect of MDM2 309 was analyzed in 2233 cases and 7164 controls from 10 case-control studies, including global registries like the Nurses’ Health Study (NHS) and the Molecular Markers in Treatment of Endometrial Cancer (MoMaTEC)." (PMID 36981012, 2023).